YBX1 (Y-box binding protein 1)
Diseases named in the same sentence as YBX1 in open-access papers (continued):
Sharing a sentence is not in itself a finding about the gene and the disease.
cancer (continued). "YBX1 is also reported to bind to CD44 and CD49f promoter and enhance CD44 expression that promotes cancer cell growth and drug resistance in breast cancer." (PMID 31358880, 2019). "Taken together, these observations indicate that SCAT7/hnRNPK/YBX1 RNP plays a crucial role in the transcriptional activation of FGFR2 and/or FGFR3 in different cancer models." (PMID 29491376, 2018). "Among analysis, MYC, Argonaute2 (AGO2), Y-box binding protein 1 (YBX1), cyclin E1 (CCNE1) were involved in organismal abnormalities and cancer." (PMID 27463019, 2016). "YBX-1 can activate E2F, PI3K/Akt/mTOR and Ras/Raf/MEK/ERK pathways to promote cancer cell proliferation." (PMID 26805816, 2016). "YBX1 has already been reported as ITAF-like protein for c-MYC and is considered as an oncogene and a marker of aggressiveness for some cancer types." (PMID 26498684, 2015). "Elevated levels of YBX1 are seen in melanoma, osteosarcomas, prostate, breast, squamous cell, lung, ovarian, thyroid, and colorectal [CRC] cancers." (PMID 26318844, 2015). "YBX1 functions as a transcription factor to regulate gene expression and can also modulate DNA repair, RNA splicing, exon skipping, drug resistance, and cancer progression through mechanisms independent of nucleic acid binding motifs." (PMID 41507134, 2026). "Moreover, we found that YBX1, in conjunction with PDH activation, promotes epithelial cell senescence and suppresses cancer cell proliferation." (PMID 40812419, 2025). "Interestingly, YBX1 can influence TNBC cancer development by regulating the MAPK signaling pathway via binding RAF1; this mechanism has a pivotal role in reverting the effects of piR-YBX1 overexpression." (PMID 40951838, 2025). "To evaluate its function in ATC drug resistance, we examined correlations between the expression of 12 m5C regulators [NSUN2-7, TRDMT1 (writers); ALKBH1, TET2, ALKBH3 (erasers); YBX1 and ALYREF (readers)] and drug sensitivity in the Cancer Therapeutics Response Portal (CTRP)." (PMID 40083919, 2025). "YBX1 is a well-established transcription factor that has been reported to induce the transcription of oncogenic genes, such as FOXA1, FZD7, and HOXC8 in cancers." (PMID 38491348, 2024). "YBX1 demonstrates the capacity to evade cell death signals, not only in cancer cells but also in immune cells." (PMID 38255791, 2024). "YBX1 assumes a pivotal role within the extracellular matrix (ECM) of tumors, orchestrating a complex interplay that shapes the ECM’s composition, remodeling dynamics, and interaction with cancer cells." (PMID 38255791, 2024). "OAV with CR3 deletion in E1A 13S exhibited high replication potential in Y-box binding protein 1 (YB-1)-positive cancer cells but replication defects in normal cells." (PMID 38528632, 2024). "YBX1 and DHX9 have been extensively studied in cancer research." (PMID 39558374, 2024). "In cancer sites affecting both males and females, biological sex did not interact with YBX1 expression and did not affect survival in this analysis (Hazard ratio = 1) (data not shown)." (PMID 38538658, 2024). "YBX1 has been identified as one of the immunogenic proteins targeted in STEMVAC trials for breast and lung cancers, contributing to the development of novel therapies and improving treatment efficacy for these cancers." (PMID 39727969, 2024). "YBX1 has been identified as a pivotal m5C reader protein that regulates the stability or translation efficiency of target RNA in various cancer types, and we found that LUAD patients with high YBX1 expression have a significantly lower overall survival rate in tumor stage III and IV." (PMID 38403250, 2024).
cancer (continued). "For instance, YBX1 is an interactive partner of lincNMR that regulates the expression of downstream RRM2, TYMS and TK1 by binding to their promoters, governing nucleotide metabolism and cell proliferation in cancer." (PMID 38491348, 2024). "In summary, targeting YBX1 may inhibit SATII RNA expression in sEVs secreted from senescent stromal cells and provide a novel therapeutic strategy for cancer treatment." (PMID 38003589, 2023). "Conversely, genetic inactivation of YBX1 had no deleterious effects on normal hematopoiesis, making it a potentially interesting therapeutic target for cancer therapy." (PMID 34465866, 2022). "Components of the methyl-YBX1-EVs-hY4F/MAPK/NF-κB signaling axis may serve as potential biomarkers and targets for cancer diagnosis and treatment." (PMID 35410432, 2022). "Although the inhibitory activity of OSU on YBX1 was validated in the context of endometriosis, the impact of such interaction on cancer-related processes was never studied, despite their altered expression in several cancers." (PMID 34356673, 2021). "Thirty-one proteins remain after screening (protein name marked in red), in which YBX1 has been reported to interact with several oncogenic lncRNAs, including TP53TG1, HULC, HOXC-AS3, and lincNMR, thereby regulating cancer progression and oncogene expression." (PMID 34266873, 2021). "In addition, a previous investigation found that a group of specific tsRNAs containing the CU-box motif binds to the cancer-promoting RNA-binding protein Y-box Binding Protein 1(YBX-1), replacing YBX-1 transcripts from the YBX-1 complex." (PMID 34907180, 2021). "Previous studies showed the Aly/REF export factor (ALYREF) and Y-box binding protein 1 (YBX1) may act as significant readers for m5C, taking part in cancer-related biological processes." (PMID 34926580, 2021). "For example, Ybx1 binds the consensus sequence, 5′‐CTGATTGG‐3′, to mediate transcriptional activation of genes involved in epithelial-to-mesenchymal transition and drug resistance, likely thereby promoting cancer progression." (PMID 32792512, 2020). "The combining of LINC00472 with YBX1 inhibited cellular EMT process and affected the mechanical properties of the cell, which may explain the decline in the ability of cancer cells to invade and metastasize." (PMID 33144579, 2020). "Furthermore, DSCAM‐AS1 (DSCAM Antisense RNA 1) has been found to play carcinogenic roles in different types of cancer and could promote the progression of PCA by interacting with YBX1." (PMID 40259205, 2025). "However, 50 transcription factors displayed similar interactions with SWI/SNF in the two cancer types, such as several zinc-finger transcription factors (ZNF512, ZNF598, ZNF609, ZNF687, and ZNF709), CTCF, ELF2, and YBX1, indicating shared gene regulation networks." (PMID 40988026, 2025). "Taken together, Tug1 enhances the recruitment of Ybx1 to the promoter regions of Pdl1 and Cd47 to promote their expression, and then inhibits the function of CD8+ T cell and the phagocytosis function of macrophages toward cancer cells, thereby regulating the antitumor immune response." (PMID 38981064, 2024). "Thus, we hypothesized that the tumor-promotive activities of YBX-1, such as phosphorylation, would be maintained and that the expression of YBX-1 mRNA would be attenuated in cancer cell lines." (PMID 34202873, 2021).
cancer (continued). "Interestingly, since both YBX1 and FOXK1 served as transcription factors in the nuclei of cancer cells, overexpression of lncRNA HUMT might lead to a chain reaction that could amplify the functions of upstream signals." (PMID 32138762, 2020). "We also included the linear isoform of nuclear factor I X (NFIX) in this experiment as a control, since its interaction with YBX1 is not known and the functional variations of the circular and linear NFIX in cancer cells are not yet well studied." (PMID 38866007, 2024).
tumor (396 papers, 1969 to 2026). "In the context of tumours, YBX1 is often overexpressed and is associated with aggressive phenotypes, increased cell proliferation, and metastasis." (PMID 39625183, 2024). "For instance, YBX1, serving as a tumor antigen linked with neuroblastoma and recurrent melanoma, can trigger specific T cell anti-tumor immune responses, which are further potentiated by regulatory T cell depletion." (PMID 39727969, 2024). "Previous studies have shown that YBX1 is associated with the malignant phenotypes in several types of tumours, including BC." (PMID 38378679, 2024). "Due to the high expression of Ybx1 in tumor-associated vasculature, Ybx1 has also been studied as a therapeutic target to suppress tumor angiogenesis." (PMID 38385749, 2024). "Among these identified proteins, YBX1, an RNA-binding protein associated with tumor cell proliferation, progression and metastasis [15‒17], was validated by western blot analysis using an anti-YBX1 antibody and RNA binding protein immunoprecipitation assay." (PMID 38899362, 2024). "Loss of YBX1 reduced tumour growth of SCC25 which was further reduced in response to BEZ235 treatment." (PMID 36949044, 2023). "Contrary to the m5C-score, YBX1 expression was associated with an active anti-tumor immune response." (PMID 36060802, 2022). "We previously showed that tumor suppressor activity of TP53TG1 is linked to its ability to block the tumorigenic activity of the RNA binding protein YBX1." (PMID 34575588, 2021). "For instance, overexpression of Ybx1 was found in tumor cells and is associated with tumor phenotype." (PMID 33278865, 2021). "Among the hundreds of potentially HOTAIR-interacting proteins, YBX1 has been associated with a range of oncogenic processes including cell proliferation, tumor progression, genomic instability, metastasis, and drug resistance." (PMID 34266873, 2021). "TP53TG1 has also shown tumor suppressor properties due to its ability to prevent the nuclear localization of the oncogenic YBX1 protein, which has been associated with cancer progression." (PMID 34575588, 2021). "At the same time, higher expression of HCG18, HMGA1, ILF2, and YBX1 was associated with a higher stem cell score and less tumor differentiation." (PMID 34527669, 2021). "Xenograft tumor formation assays further demonstrated that loss of YBX1 in HK1 cells delayed tumor growth in nude mice." (PMID 33976741, 2021). "Taken together, these data strongly argue for a model in which methylation of YBX1 at R205 modulates its tumor-associated functions in CRC under basal conditions." (PMID 32985589, 2020). "The tumours with more than 3 cm (classified as T3) didn’t present an association with YBX1 RNA levels." (PMID 31461477, 2019). "Two decades ago, overexpression of the Y-box-binding protein 1 (YB-1)/its nuclear localization were found to be associated with tumor phenotype." (PMID 29805738, 2018). "Specifically, this type of tumor-suppressive of YBX1 loss was associated with decreased glycolytic phenotypes." (PMID 29029484, 2017). "Y-box binding protein-1 (YB-1), a member of cold-shock protein superfamily, has been demonstrated to be associated with tumor malignancy, and is proposed as a prognostic marker in multiple carcinomas." (PMID 25993060, 2015). "The multifunctional oncoprotein Y-box binding protein-1 (YB-1) and the pleiotropic cytokine interleukin 6 (IL-6) have both been implicated in tumor cell metastasis and EMT, but via distinct pathways." (PMID 26512918, 2015). "Nuclear shuttling of YBX1 has been associated with its increased tumor promoter activity, and has been shown to occur upon stimulation with IL-1β." (PMID 26318844, 2015). "Expression of Y-box binding protein-1 (YB-1) is associated with tumor progression and drug resistance." (PMID 21392397, 2011). "The upregulated expression of YBX1 in various tumours is associated with poor prognosis." (PMID 40088428, 2025).
tumor (continued). "Moreover, heightened YBX1 levels are significantly associated with tumor differentiation, size, and lymph node metastasis in solid tumor patients, underscoring its role in tumor progression." (PMID 40799245, 2025). "Moreover, YBX1 has been reported to be aberrantly expressed in multiple cancers and closely associated with tumour progression and metastasis." (PMID 40176113, 2025). "Additionally, YBX1 has been implicated in promoting tumor progression through the PI3K/AKT signaling pathway in laryngeal squamous cell carcinoma (LSCC)." (PMID 40799245, 2025). "YBX1 expression levels and subcellular localization could serve as valuable prognostic markers, helping predict tumor aggressiveness and recurrence risk." (PMID 38255791, 2024). "Consequently, YBX1 can serve as an effective diagnostic and prognostic biomarker, aiding in tumor diagnosis and predicting invasiveness and recurrence risk." (PMID 39727969, 2024). "Secondly, the risk prediction models incorporating stemness, methylation, and moonlighting genes associated with YBX1 can furnish valuable insights into the prognosis and survival of tumor patients, serving as pivotal prognostic tools for predicting outcomes and survival rates." (PMID 39727969, 2024). "YBX1’s involvement in constructing tumor risk prediction models is noteworthy." (PMID 39727969, 2024). "Additionally, Y box binding protein 1 (YB-1), a well-known oncoprotein, is associated with tumor immune evasion and drug resistance." (PMID 39285476, 2024). "However, focusing on patients with localised tumour at diagnosis, a marginal association between the polymorphism Y-box binding protein 1 (YBX1) rs10493112 and PFS was detected among those treated with AbA." (PMID 39337362, 2024). "YBX1, a transcriptional activator, is associated with tumorigenesis and tumor development." (PMID 37370092, 2023). "Given the strong positive correlation between MYC and YBX1 as well as their corresponding target genes in CD133-high FN RD cells, we decided to focus on characterizing the loss-of-function effects of MYC and YBX1 on RMS tumor growth and stem cell function as well as their potential interactions." (PMID 37345125, 2023). "In castration-resistant prostate cancer (CRPC) cells, VER-155008 suppressed the expression of full-length androgen receptor (AR) and AR splice variant 7 (ARv7) through Y-box binding protein 1 (YB-1) inhibition, which makes it an attractive anti-tumor agent for treating CRPC." (PMID 37189349, 2023). "YBX1 protein is the most common tumor-associated antigen and can also induce T cell response." (PMID 35365216, 2022). "Therefore, circ-SAR1A suppression, causes an overexpression of miR-382, which blocks YBX1 expression, thus preventing tumor expansion." (PMID 35813211, 2022). "All results demonstrated that YBX1 could reverse the suppression of tumor progression caused by knockdown of FOXD3-AS1." (PMID 34395290, 2021). "However, limited knowledge is known about the underlying mechanism by which YBX1 promotes tumor progression." (PMID 29029484, 2017). "Similarly, the higher pathological component risk rating, the more proportion of YBX1 and CDC25a expression in tumor lesions." (PMID 27384875, 2016). "Y-box binding protein-1 (YB-1) is a transcription and translation factor that alters the expression of at least ten genes strongly linked to drug resistance and tumour cell growth such as the epidermal growth factor receptor (EGFR) and the human epidermal growth factor receptor-2 (HER-2)." (PMID 20844753, 2010). "Tumor-specific CRISPR knockouts or point mutants of YBX1, HNRNPA2B1, or ALIX (e.g., SUMO-site variants) could test their roles in exosomal miR-21, miR-200, miR-210 and PD-L1 loading, and the resulting effects on migration, T cell cytotoxicity, and TAM polarization." (PMID 41462674, 2025). "Thus, p16INK4a 5′ UTR variants may block this potential tumor suppressive function of YBX1, while maintaining its oncogenic transcriptional repression activity." (PMID 26498684, 2015).